TNF (tumor necrosis factor)
Diseases named in the same sentence as TNF in open-access papers (continued):
Sharing a sentence is not in itself a finding about the gene and the disease.
Insulin resistance (continued). "A proinflammatory cytokine cascade, including interleukin-6, tumor necrosis factor-alpha, and Interleukin-1 beta, disrupts insulin signaling pathways and leads to insulin resistance." (PMID 40725663, 2025). "This receptor mediates inflammatory pathways triggered by TNF-α, disrupting insulin signaling and promoting insulin resistance." (PMID 40153192, 2025). "TNF-α activates JNK, which is a kinase that causes insulin resistance via serine phosphorylation of IRS-1." (PMID 40274715, 2025). "For instance, Zhao (2021) discusses how TNF-α promotes insulin resistance via the TNF-α/IKKβ/IKβ/NF-κB signaling pathway—a process heavily reliant on the phosphorylation state of these proteins." (PMID 40129771, 2025). "Studies have shown that TNF-α induces insulin resistance and disrupts lipid metabolism, leading to glucose and lipid abnormalities." (PMID 41244040, 2025). "TNF‐α reduces insulin‐dependent glucose uptake by impeding serine autophosphorylation of insulin receptor substrate‐1, which inhibits circulating insulin, indicating an involvement of TNF‐α in insulin resistance." (PMID 39355932, 2025). "In humans, TNF levels are elevated in type 2 diabetes (T2D), contributing to glucose intolerance and insulin resistance." (PMID 40453076, 2025). "TNF‐α is the most potent pro‐inflammatory cytokine that contributes to the development of insulin resistance." (PMID 40918166, 2025). "Compared to IL-6 and TNF-α, which also contribute to systemic inflammation in PCOS, IL-18 appears to have a stronger association with insulin resistance." (PMID 40385768, 2025). "A moderate positive correlation was observed between the steatosis area and TNF-α (r=0.5254, P=0.0366) and insulin resistance (r=0.5965, P=0.0189)." (PMID 40862455, 2025). "Adipose tissue is the largest endocrine organ that secretes several pro-inflammatory cytokines and adipokines, including leptin, Tumor Necrosis Factor α (TNF-α), and interleukin (IL)-6, which affect liver inflammation and insulin resistance." (PMID 40002806, 2025). "TNF-α is known to interfere with insulin signaling, which leads to insulin resistance, a core feature in PCOS." (PMID 40385768, 2025). "In fact, elevated levels of TNF-α were reported in DM patients and IL-6 was considered to mediate adverse metabolic effects and contribute to insulin resistance." (PMID 40230621, 2025). "While IL-6 and TNF-α contribute directly to insulin resistance and inflammation, leptin plays an additional role in reproductive dysfunction by influencing ovarian steroidogenesis and follicular maturation." (PMID 40385768, 2025). "One of the most compelling findings in recent insulin resistance research involves experimental models using TNF-α-treated 3T3-L1 adipocytes." (PMID 40807540, 2025). "Pro-inflammatory cytokines such as TNF-α, IL-1β, and IL-6 produced by macrophages contribute to insulin resistance and inflammation in diabetes." (PMID 41472730, 2025). "In scenarios of insulin resistance, low-grade inflammation plays a prominent role in the dysfunction of insulin signaling, mainly through cytokines like tumor necrosis factor-alpha (TNF-α) and interleukin-6 (IL-6)." (PMID 40563357, 2025). "Key pro-inflammatory cytokines, such as tumor necrosis factor-alpha (TNF-α), interleukin (IL)-17, and IL-23, enter systemic circulation, promoting endothelial dysfunction, oxidative stress, insulin resistance, and a prothrombotic state." (PMID 40870891, 2025). "Excess adipose tissue, particularly visceral fat, induces insulin resistance through the release of pro-inflammatory cytokines such as tumor necrosis factor-alpha (TNF-α) and interleukin-6 (IL-6)." (PMID 41396032, 2025). "The increase in serum levels of tumor necrosis factor-alpha (TNF-α), which can originate from LPS, can initiate and worsen insulin resistance." (PMID 40270511, 2025).
Insulin resistance (continued). "Key findings indicate that adipokines, interleukins, and tumor necrosis factor alpha play significant roles in inflammatory responses and insulin resistance, further exacerbating cardiovascular dysfunction." (PMID 40699839, 2025). "It is frequently associated with systemic inflammation, characterized by elevated levels of TNF-α and IL-6, and metabolic dysregulation, including insulin resistance." (PMID 40093012, 2025). "Supporting the observation of insulin resistance in KO mice, we found higher expression of inflammatory cytokines, including TNFα, IFNγ, IL-1β, IL-6 and IL-22, in the muscles of KO mice fed with normal diet, compared to the control mice." (PMID 41234234, 2025). "Increased pro-inflammatory cytokines, such as TNFα, IL-6, and adiponectin, have been shown to contribute to endothelial dysfunction, oxidative stress, and insulin resistance." (PMID 40243674, 2025). "Increased pro-inflammatory cytokines such as TNF-α and IL-6, along with adiponectin, have been shown to contribute to endothelial dysfunction, oxidative stress, and insulin resistance." (PMID 40076485, 2025). "This reduction is thought to exacerbate insulin resistance by allowing the unchecked activity of pro-inflammatory cytokines such as TNF-α and IL-6, which impair insulin receptor signaling through pathways like NF-κB and JNK." (PMID 40804870, 2025). "While IL-6 and TNF-α promote insulin resistance and chronic inflammation, VEGF plays a dual role by contributing to both inflammation and pathological ovarian angiogenesis." (PMID 40385768, 2025). "As adipose tissue increases, levels of TNF-α also rise, which alters glucose receptor phosphorylation and contributes to the development of insulin resistance." (PMID 41155647, 2025). "Elevated TNF-α and IL-6, central to hepatic inflammation and systemic insulin resistance, are potential targets for anti-cytokine therapies currently evaluated in metabolic disease." (PMID 41220583, 2025). "Another study uncovered that while adipose tissue IL-6 is the main contributor to insulin resistance, IL-1β and TNF-α cooperativity increase IL-6 expression by promoting CREB binding and H3K14 acetylation at the IL-6 promoter region." (PMID 41228440, 2025). "For example, biologics such as TNF-α inhibitors have shown limited effectiveness in addressing metabolic alterations, including insulin resistance and lipid dysregulation, which are frequently observed in IBD patients." (PMID 40283915, 2025). "Elevated temperatures trigger inflammatory cytokines like TNF-α and IL-6 in adipose tissue, which disrupt insulin signaling and contribute to insulin resistance." (PMID 41036090, 2025). "Excess adipose tissue can elevate the expression of inflammatory cytokines (such as TNF-α) and adipokines (like leptin and resistin), both of which contribute to the pathogenesis of insulin resistance by disrupting insulin signaling and action." (PMID 40724174, 2025). "Studies have shown that TNF-a, Cas-9, and Cas-3 expression increases under insulin resistance conditions." (PMID 40729004, 2025). "The pro-inflammatory cytokines released in both conditions, such as TNF-α, IL-6, and IL-1β, impair insulin receptor signaling, leading to insulin resistance." (PMID 41007787, 2025). "Both diabetic and prediabetic patients also have higher TNF-α levels than their lean counterparts, which correlate strongly with increased insulin resistance." (PMID 41226411, 2025). "Elevated levels of IL-6 and TNF-α in individuals with depression contribute to insulin resistance and pancreatic beta-cell dysfunction, creating a vicious cycle of metabolic and psychological dysregulation." (PMID 40218134, 2025). "TNF-α is a key mediator of insulin resistance and endothelial dysfunction in diabetes mellitus and thrombotic states." (PMID 40002353, 2025).
Insulin resistance (continued). "Increased M1 macrophages secrete pro-inflammatory mediators such as TNF-α, IL-1β and resistin, which act on adipocytes to induce a state of insulin resistance, leading to a positive feedback loop of inflammation and insulin resistance." (PMID 40084146, 2025). "Pathways linked to TNF-α and IL-6/JAK/STAT3 signaling are well-established contributors to adipose inflammation and systemic insulin resistance." (PMID 41148235, 2025). "These invading immune cells secrete several pro-inflammatory cytokines like TNF-α, IL-6, and IL-1β that assist in the development of insulin resistance along with other metabolic dysfunctions." (PMID 40218884, 2025). "H. pylori infection induces systemic inflammation through the release of pro-inflammatory cytokines such as TNF-α, IL-1, and IL-6, which disrupt insulin signaling pathways and exacerbate insulin resistance." (PMID 40551731, 2025). "Recent research has been shown that activation of the NLRP3 inflammasome in adipocytes reduces insulin-dependent glucose uptake and contributes to TNF-α-induced insulin resistance." (PMID 40583106, 2025). "As a pro-inflammatory cytokine, TNF-α reduction is likely to alleviate insulin resistance and cardiovascular risks." (PMID 40842498, 2025). "TNF-α overexpression in adipose tissue decreases peripheral glucose uptake in response to insulin, leading to insulin resistance." (PMID 40362446, 2025). "Abnormal fat accumulation not only releases various inflammatory factors (e.g., tumor necrosis factor-α and interleukin-6) but also disrupts insulin signaling, further worsening insulin resistance." (PMID 39920728, 2025). "Tumor necrosis factor-α (TNF-α): TNF-α contributes to inflammation, endothelial dysfunction, atherosclerosis, and insulin resistance." (PMID 40001586, 2025). "The R-25 °C group, compared to the 13 °C group, was enriched in pathways related to ‘insulin resistance’, ‘TNF signaling’, and ‘IL-17 signaling’." (PMID 40002409, 2025). "In particular, TNF exacerbates insulin resistance by inhibiting insulin receptor phosphorylation and GLUT4 translocation." (PMID 41266905, 2025). "In individuals with NAFLD, lipotoxicity, insulin resistance, and endotoxins trigger the activation of proinflammatory cytokines such as tumor necrosis factor-α (TNF-α), interleukin-1α (IL-1α), interleukin-1β (IL-1β), interleukin-6 (IL-6), and resistin." (PMID 39275255, 2024). "MetS induces chronic low-level inflammation with a constant increase in TNF-α and IL-6 cytokines, especially among obese individuals, and develops insulin resistance and TG circulation." (PMID 38785834, 2024). "Results of other studies disclosed that probiotic administration through suppressing or decreasing TNF- α exerted therapeutic effects such as improving insulin resistance in diabetic patients or animals." (PMID 38504163, 2024). "Anti-TNF-α treatment strategies have been developed to reduce the incidence of insulin resistance and T2DM." (PMID 39070321, 2024). "Adipose cells, especially those belonging to visceral fat, release pro-inflammatory cytokines such as TNF-α or IL-6 and adipokines such as leptin, which promote insulin resistance and inflammation." (PMID 38999756, 2024). "Cytokines play a role in this insulin resistance, with tumour necrosis factor-alfa (TNF-α) and interleukin-1 (IL-1) inhibiting post-receptor signalling, and epinephrine and cortisol reducing insulin-mediated uptake." (PMID 38473761, 2024). "Dysfunctional adipocytes and infiltrated M1 macrophages in adipose tissue release TNF-α, which has atherogenic effects and promotes insulin resistance and dyslipidemia." (PMID 38399430, 2024). "A study showed restoration of TNF-mRNA levels and attenuation of insulin resistance in mice when supplemented with a purple corn diet." (PMID 39125340, 2024). "It restores the adipocytokine balance, reducing elevated TNF-α levels, which is directly involved in insulin resistance development." (PMID 39273582, 2024).
Insulin resistance (continued). "Its anti-inflammatory effects are mediated through the downregulation of IL-6 and TNF-α and the upregulation of IL-10, thereby mitigating chronic inflammation that contributes to insulin resistance and β-cell dysfunction." (PMID 39796549, 2024). "Leptin, adiponectin, and resistin are key markers, along with pro-inflammatory cytokines like TNFα, IL-1β, and IL-6, which also play roles in insulin resistance." (PMID 39407941, 2024). "Previous research indicates that levels of tumor necrosis factor (TNF), interleukin (IL)-1, and IL-6 are elevated in AS and contribute to the onset of insulin resistance." (PMID 39649224, 2024). "For instance, one study explored the anti-insulin resistance activity of lrisin (a natural product) in 10 ng/ml TNF-α -induced HepG2 cells." (PMID 39749015, 2024). "TNF-α, another pro-inflammatory factor in diabetes, leads to cardiac dysfunction, oxidative stress and insulin resistance." (PMID 39204151, 2024). "Supporting the role of TNF-α in the pathogenesis of diabetes, cohorts receiving anti-TNF-α therapy, particularly infliximab, have shown significantly lower mean blood glucose levels and reduced insulin resistance." (PMID 38842591, 2024). "PP4 also functions as a key regulator of tumor necrosis factor (TNF)-α-induced insulin resistance in liver." (PMID 38568153, 2024). "Two studies in patients with rheumatoid arthritis undergoing infliximab (monoclonal antibody against TNF-α) therapy showed a rapid beneficial effect on insulin resistance and sensitivity." (PMID 39606781, 2024). "TNF-α and IL-6 are not only pivotal in the inflammatory response but also directly exacerbate metabolic dysfunctions, leading to insulin resistance and the advancement of atherosclerosis, thereby linking obesity directly with increased cardiovascular risk." (PMID 39064298, 2024). "Gene enrichment analysis identified pathways involved in insulin resistance, adherens junctions, metabolic processes, IL-17, TNF-α, cAMP, relaxin, and AGE-RAGE in diabetic complications." (PMID 39458839, 2024). "In this study, ferulic acid was investigated for its potential in suppressing TNF-α-treated inflammation and insulin resistance in adipocytes." (PMID 38257186, 2024). "Currently, chronic inflammation mediated by cytokines (IL-17, TNFα, adiponectin, IL-6) is implied in the development of insulin resistance." (PMID 39598018, 2024). "TNF-α directly contributes to insulin resistance by activating stress kinases, thus blocking insulin signal transduction." (PMID 38683749, 2024). "Inflammatory factors such as TNF-α, IL-6, and C-reactive protein are known to contribute to insulin resistance in GDM." (PMID 39759105, 2024). "Insulin resistance in MASLD arises from an imbalance between insulin sensitizing adipokines, such as adiponectin and leptin, and cytokines that promote insulin resistance like TNF-α." (PMID 39064282, 2024). "The accumulation of TG in adipocytes can lead to a rise in resistin, TNF-α, and interleukin 6, which can result in insulin resistance." (PMID 38867151, 2024). "Seprina3 is highly expressed in AT, where it regulates preadipocyte differentiation, AT inflammation, and tumour necrosis factor alpha (TNF-α)-induced insulin resistance." (PMID 39064738, 2024). "As a signaling molecule, IKKB is also involved in TNF-α induced insulin resistance through two main pathways." (PMID 40302954, 2024). "Jansen’s team observed that 1,2-Dilinoleoyl-sn-glycero-3-phosphocholine enhances adipocyte catabolism and apoptosis through a TNF-α-dependent pathway, thereby alleviating insulin resistance via PPARα-mediated inhibition of myocyte inflammation." (PMID 39050247, 2024). "TNF-alpha is highly expressed in adipose tissues of obese humans and animals, inducing various characteristics of insulin resistance in experimental animals." (PMID 39120321, 2024).
Insulin resistance (continued). "Inflammatory cytokines, including tumor necrosis factor (TNF-α) and interleukins, contribute to insulin resistance, Aβ accumulation, and tau phosphorylation." (PMID 38724582, 2024). "For example, performing 8 weeks of HIIT has led to a significant decrease in the serum concentration of tumor necrosis factor-α (TNF-α) and chemerin, and improved body composition and insulin resistance in obese women." (PMID 38626052, 2024). "Elevated levels of TNF-α induce insulin resistance and decrease the expression of glucose transporters GLUT-4." (PMID 39857860, 2024). "Spinach aids insulin resistance by inhibiting increased levels of serum C-reactive protein, tumor necrosis factor (TNF)-α, and Interleukin-6." (PMID 39519546, 2024). "Autophagy-related DEGs were associated with autophagy, cell apoptosis, nucleotide oligomerization domain (NOD)-like receptor signaling, tumor necrosis factor (TNF) signaling, and insulin resistance pathways." (PMID 38464517, 2024). "SREBP-1c is implicated in the generation of diacylglycerol (DAG) and ceramides, molecules that induce inflammation by interacting with tumor necrosis factor-α (TNF-α), thereby exacerbating insulin resistance." (PMID 39057041, 2024). "The role of TNF in insulin resistance has been better studied than the role of TNF in atherosclerosis." (PMID 38396488, 2024). "The direct implication of TNF-α in inducing insulin resistance in different tissues (skeletal and adipose) has been well documented, with TNF-α suppression leading to improved insulin sensitivity in vivo." (PMID 39458839, 2024). "By upregulating PTEN and suppressing the AKT/eNOS/NO signalling pathway, TNF-alpha also contributes to vascular insulin resistance." (PMID 39251829, 2024). "TNFα induces phosphorylation of PPARγ at Ser-273 in murine adipocytes subsequently promoting insulin resistance." (PMID 38735390, 2024). "Reports have shown that TNF-α can impede insulin transmission and influence glucose metabolism, possibly playing a pivotal role in the onset of obesity and insulin resistance." (PMID 39101085, 2024). "For instance, IL-6 has been implicated in glucose metabolism and adipocytes’ function, contributing to insulin resistance and systemic inflammation, while the role of TNF-α in promoting insulin resistance is well documented." (PMID 39125408, 2024). "In NAFLD and NASH, insulin resistance and inflammatory cytokines, such as TNF-α and IL-6, are key drivers, with miR-122 and miR-34a playing significant roles in lipid metabolism and inflammation." (PMID 38928187, 2024). "For example, a low dose of 30 μM DHA at physiological or nutritional levels ameliorated palmitate (500 μM)-induced insulin resistance and the expression of inflammatory genes (TNFα and IL-6) in C2C12 cells." (PMID 38501107, 2024). "Chronic hyperglycemia and insulin resistance trigger systemic inflammation, leading to the release of pro-inflammatory cytokines, such as interleukin-6 (IL-6) and tumor necrosis factor-alpha (TNF-α)." (PMID 39728750, 2024). "TNFα is crucial in insulin resistance, as it interferes with insulin receptor signalling by phosphorylating ISR1/2, inhibiting Akt, and therefore diminishing the translocation of GLUT4 to the plasma membrane." (PMID 38953241, 2024). "It is an inhibitory cytokine that can attenuate the apoptosis of β-cells, suppression of insulin secretion, and peripheral insulin resistance induced by pro-inflammatory cytokines such as IL-6 and TNF-α." (PMID 39574905, 2024). "High levels of inflammatory markers like C-reactive protein (CRP), interleukin-6 (IL-6), and tumour necrosis factor-alpha (TNF-α) are strong predictors of CVD risk and are also associated with insulin resistance and metabolic syndrome." (PMID 38999799, 2024). "The increase in blood sugar can induce insulin resistance, leading to liver lipid metabolism disorder and low-grade systemic inflammation, increasing inflammatory mediators such as IL-6 and TNF-a in the plasma." (PMID 38596638, 2024).